C1QTNF3 (C1q and TNF related 3)
Synonyms: CORS26; CTRP3; Cors; Corcs; 2310005P21Rik; Cors-26; C1ATNF3
Tractability: Antibody: UniProt places it where antibodies can reach, with high confidence; UniProt predicts a signal peptide or a membrane-spanning region; its Gene Ontology location is reachable by antibodies, with medium confidence.
Gene: Protein-coding gene on chromosome 5 (34,017,858 to 34,043,228, reverse strand). Ensembl gene ENSG00000082196.
Subcellular location: Secreted
Subcellular location (Human Protein Atlas): Golgi apparatus; Predicted to be secreted
Gene Ontology:
Molecular function: identical protein binding; protein binding
Biological process: fat cell differentiation; intracellular triglyceride homeostasis; negative regulation of gluconeogenesis; negative regulation of inflammatory response; negative regulation of interleukin-6 production; negative regulation of monocyte chemotactic protein-1 production; negative regulation of non-canonical NF-kappaB signal transduction; positive regulation of adiponectin secretion; positive regulation of cytokine production; maintenance of synapse structure; trans-synaptic signaling, modulating synaptic transmission; chemical homeostasis; regulation of intracellular signal transduction
Cellular component: extracellular exosome; membrane; synapse; synaptic cleft; extracellular region; protein-containing complex
Genetic constraint (gnomAD): Loss-of-function variants: 21 observed, 29.38 expected, observed/expected ratio (o/e) 0.71, 90% interval 0.51 to 1.03. The upper end of that interval is the gene's LOEUF score, 1.03, which puts it in group 4 of 6, group 1 being the genes least tolerant of losing a copy. Missense variants: 358 observed, 416.64 expected, observed/expected ratio (o/e) 0.86, 90% interval 0.79 to 0.94. Synonymous variants: 155 observed, 154.56 expected, observed/expected ratio (o/e) 1, 90% interval 0.88 to 1.15.
Homologues: Orthologues: macaque AMACR (99% identical), dog C1QTNF3 (97% identical), pig C1QTNF3 (96% identical), rabbit C1QTNF3 (96% identical), guinea pig C1QTNF3 (95% identical), mouse C1qtnf3 (93% identical), rat C1qtnf3 (92% identical), tropical clawed frog c1qtnf3 (68% identical). Paralogues in human: COL8A2 (29% identical), COL8A1 (28% identical), COL10A1 (27% identical), OTOL1 (25% identical), C1QTNF9 (25% identical), C1QTNF9B (24% identical), C1QB (24% identical), C1QC (23% identical), C1QL2 (23% identical), C1QTNF2 (23% identical), C1QTNF7 (23% identical), ADIPOQ (22% identical), and 11 more.
Diseases named in the same sentence as C1QTNF3 in open-access papers:
C1QTNF3 is named in the same sentence as 116 diseases in open-access papers, as found by Europe PMC text mining. Sharing a sentence is not in itself a finding about the gene and the disease. The quoted sentences say what the papers report.
Obesity (37 papers, 2013 to 2025). Accumulation of substantial excess body fat. "The circulating levels of the C1QTNF3 were however unaffected by both diet-induced obesity and experimental breast cancer." (PMID 35720277, 2022). "In an additional HFD/obesity study in males, we found that C1qtnf3 is regulated in an adipose depot-specific manner." (PMID 35720277, 2022). "Patients with type-2 diabetes have lower circulating C1QTNF3 levels and visceral adipose tissue C1qtnf3 levels are reduced in obesity/insulin resistant conditions, but less is known about C1qtnf3 regulation in subcutaneous adipose tissue." (PMID 35720277, 2022). "Also, chronic HFD-feeding/obesity upregulated the IWAT C1qtnf3 expression in both males and females, but to a lesser extent than in tumor-bearing mice." (PMID 35720277, 2022). "Here, we found that IWAT C1qtnf3 expression increases in response to both a growing a tumor and to HFD-induced obesity, and this C1qtnf3 expression correlated with the expression of several macrophage markers and chemokines." (PMID 35720277, 2022). "Moreover, the IWAT SVF expression of C1qtnf3 was increased in HFD-induced obese female and male mice, while the adipocyte C1qtnf3 expression remained low and unaltered by HFD/obesity." (PMID 35720277, 2022).
diabetes (33 papers, 2013 to 2025). "C1qTNF3 is a metabolic hormone with beneficial anti-inflammatory properties, and prior studies have found that obese individuals are at lower risk of incident TB but greater risk of diabetes, which in itself is suggested as a TB risk factor." (PMID 30990820, 2019).
Insulin resistance (17 papers, 2013 to 2024). Increased resistance towards insulin, that is, diminished effectiveness of insulin in reducing blood glucose levels. "Pharmacological treatment with C1QTNF3, associated with a 3-fold elevation of circulating C1QTNF3 levels, lowers glucose levels in normal and insulin-resistant ob/ob mice." (PMID 35720277, 2022).
hepatoma (6 papers, 2013 to 2022). "One previous study showed that miR-495-targeted C1QTNF3 inhibits hepatocellular carcinoma cell growth." (PMID 36311798, 2022).
rheumatoid arthritis (6 papers, 2016 to 2024). A chronic, systemic autoimmune disorder characterized by inflammation in the synovial membranes and articular surfaces. "Other studies have implicated low levels of C1qTNF3 in other inflammatory diseases such as rheumatoid arthritis, heart disease, lipid dysregulation, and apoptosis." (PMID 30990820, 2019). "Previously, we showed that CTRP3 is highly expressed in rheumatoid arthritis (RA) models, and that the development of collagen-induced arthritis (CIA) is exacerbated in C1qtnf3–/– mice in an complement-independent mechanism." (PMID 34925309, 2021). "Considering that NF-κB signalling and HIF-2α are deeply involved in rheumatoid arthritis as well as OA29–32, C1qtnf3 may regulate the inflammatory arthritis through suppressing the NF-κB - HIF-2α axis, similar to the present findings." (PMID 32214220, 2020).
Arthritis (5 papers, 2020 to 2021). Inflammation of a joint. "Previously, we showed that the expression of C1qtnf3, encoding CTRP3, is highly augmented in joints of autoimmune arthritis models and CTRP3-deficiency exacerbates collagen-induced arthritis in mice." (PMID 34925309, 2021). "C1qtnf3/Ctrp3 is highly expressed in several mouse models of arthritis and attenuates systemic inflammation and arthritis severity, suggestive of a protective role." (PMID 33670905, 2021).
breast carcinoma (3 papers, 2014 to 2024). "On the other hand, our study shows that C1QTNF3 expression is regulated in a similar manner as many pro-inflammatory chemotactic factors in breast cancer-associated IWAT." (PMID 35720277, 2022). "The negative effect of C1QTNF3 on macrophage respiration was to us unexpected findings and prompted us to also test the effect of C1QTNF3 on mitochondrial function in cultured pre-adipocytes, adipocytes, and E0771 breast cancer cells." (PMID 35720277, 2022). "The C1qtnf3 expression was even lower in peritoneal macrophages than in 3T3-L1 adipocytes and undetectable in E0771 breast cancer cells." (PMID 35720277, 2022). "Here, we show that mRNA and protein levels of C1QTNF3 are upregulated in IWAT in response to breast cancer and that C1QTNF3-neutralizing antibody treatment inhibits the breast cancer-induced macrophage recruitment to IWAT in HFD-induced obese mice." (PMID 35720277, 2022). "We thus hypothesized that C1QTNF3 plays a role in macrophage regulation in breast cancer and/or subcutaneous adipose tissue remodeling." (PMID 35720277, 2022). "In line with this hypothesis, our data show that C1QTNF3 contributes to breast cancer-induced macrophage infiltration in IWAT." (PMID 35720277, 2022). "We believe that this lack of glucose-regulatory effect of C1QTNF3 neutralizing antibodies is not surprising; firstly, breast cancer bearing mice did not display altered serum C1QTNF3 levels (this study) and mice lacking C1QTNF3 have unaltered glucose metabolism." (PMID 35720277, 2022).
spinal muscular atrophy (3 papers, 2019 to 2022). A motor neuron disease that affect the muscles, and characterized by muscle weakness and atrophy resulting from progressive degeneration and irreversible loss of the anterior horn cells in the spinal cord (i.e., lower motor neurons) and the brain stem nuclei. "In rodents, studies on Spinal Muscular Atrophy (SMA) led to the identification of CTRP3 (C1QTNF3, C1q/Tumor Necrosis Factor-related protein 3), which is secreted by muscle and promotes protein synthesis locally in motor neurons, via the activation of mTOR." (PMID 32982690, 2020).
autoimmune disease (2 papers, 2015 to 2021). A disorder resulting from loss of function or tissue destruction of an organ or multiple organs, arising from humoral or cellular immune responses of the individual to their own tissue constituents. "In this study, we showed that CTRP3 was highly expressed in Th17 cell, a key player for the development of autoimmune diseases, and Th17 cell differentiation was augmented in C1qtnf3–/– mice." (PMID 34925309, 2021).
prostate carcinoma (2 papers, 2015 to 2020). A carcinoma that arises from epithelial cells of the prostate gland. "A prognostic prediction model reveals that C1QTNF3 is a promising biomarker for prostate cancer." (PMID 32633782, 2020).
experimental autoimmune encephalomyelitis (1 paper, 2021). An autoimmune demyelinating disease of the central nervous system that is produced experimentally in animals by the injection of homogenized brain or spinal cord in Freund's adjuvant. "The development of myelin oligodendrocyte glycoprotein (MOG)-induced experimental autoimmune encephalomyelitis was enhanced in C1qtnf3–/– mice associated with increase of Th17 cell population." (PMID 34925309, 2021). "Furthermore, we examined the effect of C1qtnf3-deficiency on the development of experimental autoimmune encephalomyelitis (EAE), in which Th17 cells play a crucial role." (PMID 34925309, 2021).
lipid metabolism disorders (1 paper, 2021). "Similar conclusions were shown in this study, and we found lipid metabolism related genes, including Angptl4, Mrap, Angptl8, and C1qtnf3, were significantly changed by disruption, suggesting that disruption induced lipid metabolism disorders in the myocardium." (PMID 33842566, 2021).
teratoma (1 paper, 2021). A non-seminomatous germ cell tumor characterized by the presence of various tissues which correspond to the different germinal layers (endoderm, mesoderm, and ectoderm). "Although the amount of their production from the teratoma is unclear, these factors have been reported to circulate in wt serum on the order of ng/mL (Prl2c, resistin, insulin growth factor 2, angiopoietin, C1qtnf3, Postn, IGFBPs, PPBP), and pg/mL (colony-stimulating factor 1)." (PMID 33888706, 2021).
viral infection (1 paper, 2022). "In this study, the knockdown of the C1QTNF3 gene in ASFV-infected PAMs resulted in the increased expression of inflammatory cytokines, thereby inhibiting viral infection." (PMID 36311798, 2022).
cancer (9 papers, 2011 to 2025). A tumor composed of atypical neoplastic, often pleomorphic cells that invade other tissues. "It is noteworthy that ADAMTS12, AMACR, SLC45A2 and C1QTNF3 are associated with cancers, which are all hallmarked by CIN (aneuploidy)." (PMID 26543751, 2015). "For instance, C1QTNF3 regulates inflammatory pathways, NEU1 modulates cellular signaling and shows therapeutic potential for cancer and immune disorders, and GPx3 is known for its antioxidant and anti-inflammatory properties." (PMID 40243471, 2025).
tumor (8 papers, 2015 to 2024). "Alternatively, the effect of C1QTNF3 on macrophage polarization is outruled by more potent macrophage polarizing factors in tumor-associated HFD-induced obese IWAT." (PMID 35720277, 2022). "We found that the elevated C1qtnf3 mRNA levels in tumor-associated IWAT was associated with a ~70% increase in released C1QTNF3 protein." (PMID 35720277, 2022). "Importantly, the increased C1qtnf3 expression in tumor-associated IWAT was associated with increased release of C1QTNF3 protein." (PMID 35720277, 2022). "We identified the C1q/TNF-related protein family member C1qtnf3 as one of the most upregulated genes that encode secreted proteins in tumor-associated inguinal adipose tissue - especially in high fat diet-induced obese mice that displayed 3-fold larger tumors than their lean controls." (PMID 35720277, 2022). "To study the potential role of C1QTNF3 in tumor immunity and/or progression, we first characterized the macrophage infiltration in E0771 tumors, tumor-associated and control IWAT and spleen of untreated lean and HFD-induced obese female mice (body weight: 23.9±0.5 vs. 36.0±2.1 g, p<0.0001)." (PMID 35720277, 2022). "Compared to those in normal tissues, APOE, STEAP4, and C1QTNF3 expressions were upregulated in tumor tissues, whereas BNIP3L and PPARGC1A expressions were downregulated." (PMID 39524226, 2024). "On the other hand, pRCC showed upregulation of TFPI2, FSTL1, FAS, and PIGR in the epithelial/tumor, C1QTNF3 and GRN in the endothelial, and ITGAX, HLA-DQA1, IL4I1, and CTSC in the immune compartments." (PMID 38703764, 2024). "Led by these data, we chose to study the role of C1QTNF3 on macrophage accumulation and tumor growth in the HFD-induced obese setting." (PMID 35720277, 2022). "We propose that locally increased C1QTNF3 levels contribute to increased IWAT macrophage accumulation in response to a growing tumor." (PMID 35720277, 2022). "To elucidate the mechanism for the inhibitory action of C1QTNF3 neutralization on tumor-induced IWAT macrophage accumulation, we analyzed the effect of C1QTNF3 treatment on chemotaxis and proliferation in bone marrow derived macrophages." (PMID 35720277, 2022). "Other genes annotated on chromosome 20 are involved in mammary gland metabolism (GHR, OXCT1), antibody production and phagocytosis of bacterial cells (C6, C7, C9, C1QTNF3), tumor suppression (DAB2), involution of mammary epithelium (OSMR) and cytokine regulation (PRLR)." (PMID 25658712, 2015). "Moreover, glucose levels changed similarly between groups after tumor implant and antibody treatment (Δglucose: -0.52±0.7 vs. -0.13±0.6 mM, p=0.7) supporting the notion that C1QTNF3, under this experimental condition, acts locally rather than acting as a classical hormone." (PMID 35720277, 2022). "In contrast, eight genes (COL1A1, COL5A1, COL1A2, COL3A1, WNT2, C1QTNF3, ADAMTS2, GXYLT2) exhibited elevated expression in tumor compared to normal tissue." (PMID 39062832, 2024). "While this C1QTNF3-stimulated macrophage population appears not to be involved in tumor progression/rejection, its role in subcutaneous adipose tissue remodeling warrants further investigations." (PMID 35720277, 2022). "However, serum levels of C1QTNF3 in tumor-bearing mice did not change, indicating that changes in local C1QTNF3 levels are more important than systemic in this context." (PMID 35720277, 2022). "Thus, IWAT C1QTNF3 affects macrophages locally in IWAT, but not in the adjacent tumor." (PMID 35720277, 2022).
infection (4 papers, 2014 to 2022). The state of being infected such as from the introduction of a foreign agent such as serum, vaccine, antigenic substance or organism. "The results show that the expression of C1QTNF3 decreased gradually with infection time, which was 69% lower in the infected group than in the uninfected group at 72 hpi." (PMID 36311798, 2022). "PAMs were infected with ASFV at a multiplicity of infection (MOI) of 0.1, and the cell samples were collected 24 h, 48 h, and 72 h postinfection (hpi) to detect the expression of C1QTNF3 and other inflammatory factors." (PMID 36311798, 2022).
C1QTNF3 also shares sentences with these, for which no sentence is quoted: type 2 diabetes (26 papers); coronary artery disease (15); cardiac hypertrophy (13); atherosclerosis (12); metabolic syndrome (12); myocardial infarction (12); Hypertension (11); metabolic disorders (11); cardiovascular disease (10); heart failure (10); endothelial dysfunction (9); acute coronary syndrome (8); Hepatic steatosis (8); myocardial ischemia (6); polycystic ovary syndrome (6); Myocardial fibrosis (5); Sepsis (5); osteosarcoma (4); acute pancreatitis (3); diabetic cardiomyopathy (3); diabetic nephropathy (3); diabetic retinopathy (3); gestational diabetes mellitus (3); Hyperglycemia (3); nonalcoholic fatty liver disease (3); prediabetes (3); acute kidney injury (2); cholestasis (2); chronic kidney disease (2); coronary artery calcification (2).
A further 69 diseases each share a sentence with C1QTNF3 in 2 papers or fewer.